TRPV1 (transient receptor potential cation channel subfamily V member 1)
Diseases named in the same sentence as TRPV1 in open-access papers (continued):
Sharing a sentence is not in itself a finding about the gene and the disease.
Sepsis (31 papers, 2011 to 2025). Sepsis is defined as life-threatening organ dysfunction caused by a dysregulated host response to infection. "We also found that the involvement of TRPV1-mediated an increase in cyclooxygenase-2 and prostaglandin E metabolite production in H2S-induced sepsis-associated alterations in mice." (PMID 35409029, 2022). "The authors concluded that TRPV1 deletion is associated with decreased macrophage-associated defenses and so TRPV1 protects against sepsis damage, possibly influencing the transition from local inflammation to systemic disease." (PMID 34200205, 2021). "Previous studies have shown that H2S caused systemic inflammation and airway inflammation via TRPV1-mediated neurogenic inflammation in sepsis and lung inflammation model, respectively." (PMID 32486252, 2020). "This evidence reveals a potential adverse effect broad TRPV1 antagonism could have in older individuals, potentially making them susceptible to the development of SIRs or sepsis." (PMID 34200205, 2021). "TRPV1 knockout mice showed higher susceptibility to sepsis compared with wild type, due to several immune deficiencies related to macrophages (e.g., reduced phagocytosis, decreased reactive oxygen species, decreased bacteria clearance, and downregulation of tumour necrosis factor α expression)." (PMID 28642799, 2017). "Indeed, TRPV1 deletion or antagonism has been associated with poorer outcome of experimental sepsis as TRPV1 blockade increases pathogen load and also facilitates the transition from a local to a systemic inflammatory response to bacteria." (PMID 25242870, 2014). "When given subcutaneously 30 minutes before CLP, the TRPV1 capsazepine treatment significantly attenuated systemic inflammation and multiple organ damage caused by sepsis, as characterized by lowered lung and liver MPO activities and histological evidence of diminished pulmonary and hepatic injury." (PMID 24278674, 2012). "In sepsis, H2S activates TRPV-1, which in turn upregulates the PGE metabolite and COX2 levels, resulting in acute lung injury." (PMID 39334911, 2024). "The neuropeptides responsible for the protective effect of TRPV1 in sepsis and the mechanisms of their activation are yet to be determined." (PMID 38731999, 2024). "Although the role of TRPV1 in inflammation, including sepsis, is mainly pro-inflammatory, there is evidence suggesting its anti-inflammatory effects in animal models of sepsis." (PMID 38731999, 2024). "We have shown that in sepsis, H2S regulates TRPV-1-mediated neurogenic inflammation by increasing the production of SP and by activating the ERK–NF-κB signaling pathway." (PMID 39334911, 2024). "It has been reported that aged Trpv1−/− knockout mice had a reduced ability to resist polymicrobial sepsis in the CLP model." (PMID 38731999, 2024). "Prior studies on TRPV1 in sepsis have yielded divergent results—some suggesting a protective role, and others a harmful role." (PMID 35610647, 2022). "In a mouse model of sepsis, TRPV1 deletion resulted in impaired phagocytes defense mechanisms, thus implying that TRPV1 acts to protect against the inflammatory condition." (PMID 35562920, 2022). "In a sepsis model, the LPS-stimulated peritoneal macrophages showed an impaired phagocytosis when TRPV1 was knock-out, suggesting the putative role of TRPV1 to potentiate macrophages." (PMID 32153564, 2020). "H2S was also shown to induce systemic inflammation and multiple organ damage characteristic of sepsis via transient-receptor potential-vanilloid-type-1-(TRPV1)-mediated neurogenic inflammation." (PMID 33330130, 2020). "In the CLP sepsis model, TRPV1 knockout mice (TRPV1 KO) exhibited more severe LPS-induced sepsis compared with wild type." (PMID 31681615, 2019). "The data indicate that TRPV1 is involved in macrophages activity and that potentially TRPV1 antagonist can be used to suppress inflammatory responses and to treat sepsis." (PMID 31681615, 2019).
Sepsis (continued). "Later, TRPV1 deletion was shown to decrease ROS production by macrophages in sepsis and to modulate the release of these mediators in other inflammatory conditions." (PMID 25242870, 2014). "In support of this finding, we show a decrease in TRPV1 expression in an in-vivo model of sepsis-induced lung injury." (PMID 23468922, 2013). "Recent results have identified the endogenous neural mediator that implicates in H2S-induced neurogenic inflammation and the molecular mechanisms by which H2S promotes TRPV1-mediated neurogenic inflammation in sepsis." (PMID 24278674, 2012). "The use of capsazepine, a selective TRPV1 antagonist, determined that H2S upregulates COX-2 and PGEM in sepsis by a TRPV1 channel-dependent mechanism." (PMID 24278674, 2012). "Taken together, results in this study showed that H2S regulates TRPV1-mediated neurogenic inflammation in polymicrobial sepsis through enhancement of SP production and activation of the ERK-NF-κB pathway." (PMID 24278674, 2012). "The role of TRPV1 in inflammation and autoimmune diseases is controversial; several studies have demonstrated a proinflammatory effect, while others have identified a protective role of TRPV1 in systemic inflammation and sepsis." (PMID 24280677, 2012). "In a more recent study, we have shown that H2S induces systemic inflammation and multiple organ damage characteristic of sepsis via transient-receptor-potential-vanilloid-type-1-(TRPV1-) mediated neurogenic inflammation." (PMID 24278674, 2012). "In conclusion, we propose that H2S regulates TRPV1-mediated neurogenic inflammation in polymicrobial sepsis through enhancement of SP production and activation of the ERK-NF-κB pathway." (PMID 21931742, 2011). "Our previous study demonstrated that H2S promotes TRPV1-mediated neurogenic inflammation in polymicrobial sepsis." (PMID 21931742, 2011). "Hydrogen sulfide (H2S) has been shown to induce transient receptor potential vanilloid 1 (TRPV1)-mediated neurogenic inflammation in polymicrobial sepsis." (PMID 21931742, 2011). "Taken together, the present findings show that H2S regulates TRPV1-mediated neurogenic inflammation in polymicrobial sepsis through enhancement of SP production and activation of the ERK-NF-κB pathway." (PMID 21931742, 2011). "Here, we show that H2S regulates TRPV1-mediated neurogenic inflammation in sepsis through upregulation of pulmonary and plasma SP." (PMID 21931742, 2011). "Taken together, these findings suggest that endogenous H2S signaled via TRPV1 which resulted in the subsequent release of SP, thereby allowing SP to elicit its potent proinflammatory effects in sepsis." (PMID 21931742, 2011). "Nevertheless, we ascertained from our data that sepsis has a significant sensory neurogenic component that involved SP and mediated by H2S in a TRPV1-dependent manner." (PMID 21931742, 2011). "Male Swiss mice were subjected to cecal ligation and puncture (CLP)-induced sepsis and treated with TRPV1 antagonist capsazepine 30 minutes before CLP." (PMID 21931742, 2011). "We found that homozygous and heterozygous Shank3 deficiency, but not Shank2 and Trpv1 deficiency, aggravates hypothermia, systemic inflammation (serum IL-6 levels), and sepsis mortality in mice, induced by lipopolysaccharide (LPS)." (PMID 36845137, 2023). "In accord, small-molecule TRPV1 agonists were shown to reduce inflammation in sepsis models." (PMID 37371563, 2023). "Therefore, the presence of the active form of TRPV1 along with its endogenous activators in the heart indicates an important role of TRPV1 signaling pathway in preventing sepsis and maintaining cardiac function." (PMID 36589466, 2022). "In systemic inflammatory diseases such as sepsis, TRPV1 has an inconsistent role." (PMID 33193423, 2020). "H2S upregulates COX-2 and prostaglandin E metabolite (PGEM) in sepsis through the TRPV1 channel." (PMID 33330130, 2020).
Sepsis (continued). "However, a contradictory study has also shown that in the same CLP model of sepsis blocking TRPV1 activity with capsazepine attenuates systemic inflammation, multiple organ damage, and mortality." (PMID 33193423, 2020). "TRPV1 KO mice further corroborate this, exhibiting elevated hypotension, hypothermia, cytokine levels, organ dysfunction, and mortality in mice with endotoxemia and polymicrobial sepsis via cecal ligation puncture (CLP)." (PMID 33193423, 2020). "Moreover, endogenous activation of cardiac TRPV1 during sepsis and endotoxemia led to the release of CGRP minimizing cardiac dysfunction." (PMID 31681615, 2019). "In murine sepsis models, genetic or pharmacologic disruption of TRPV1 can affect mortality, blood bacteria clearance, and cytokine response, in such a pattern that may vary according to the sepsis-inducing events and the methods of TRPV1 disruption." (PMID 26482920, 2016). "Transient receptor potential vanilloid 1 (TRPV1) modulates macrophage-mediated responses in sepsis, but its role in other pathogenic diseases has never been addressed." (PMID 25242870, 2014). "Therefore, this study showed for the first time that H2S induces systemic inflammation and multiple organ damage characteristic of sepsis via TRPV1-mediated neurogenic inflammation." (PMID 24278674, 2012). "Also, a recent study has shown that H2S upregulates cyclooxygenase-2 (COX-2) and prostaglandin E metabolite [PGEM] in sepsis-evoked acute lung injury via TRPV-1 channel activation." (PMID 24278674, 2012). "However, none has investigated the detailed signaling mechanism of endogenous H2S in mediating neurogenic inflammation in polymicrobial sepsis in a TRPV1 relevance context." (PMID 21931742, 2011). "Importantly, our earlier work has demonstrated that H2S promotes TRPV1-mediated neurogenic inflammation in polymicrobial sepsis." (PMID 21931742, 2011). "Therapy with TRPV1 antagonists in aged patients may potentially suppress the systemic inflammatory response, thereby reducing their resistance to bacterial infection and sepsis." (PMID 38731999, 2024). "In addition to possible carcinogen risks, preclinical studies may provide evidence of TRPV1 functionality playing a role in the development of sepsis." (PMID 34200205, 2021). "Activation of TRPV1 by capsaicin is associated with the release of two proinflammatory neuropeptides, substance P (SP) and calcitonin gene related peptide (CGRP), which may increase recruitment of leukocytes to the tissue and help in protection against sepsis." (PMID 28642799, 2017). "Capsaicin, a specific agonist of TRPV1 ion channel, can suppress inflammation via a TRPV1-independent mechanism by directly targeting PKM2-LDHA and COX2 in sepsis." (PMID 39967868, 2025). "We studied the anti-inflammatory effects and TRPV1-dependent mechanisms of OLDA in models of inflammation and sepsis." (PMID 35610647, 2022). "Wanner and colleagues showed that TRPV1 antagonism in young (12 wks) mice resulted in increased LPS-induced mortality, demonstrating an anti-inflammatory role for TRPV1 in SIRS, supporting earlier work in the CLP sepsis model." (PMID 34200205, 2021). "In summary, the evidence presented here indicates that host-derived H2S often plays a pro-inflammatory role in animal models of sepsis, acting via SP, NK1R, or TRPV1." (PMID 33330130, 2020). "Therefore, in the present study, we hypothesized that SP is one important neural element that implicates in H2S-induced neurogenic inflammation in sepsis through a TRPV1 channel-dependent mechanism, and that H2S regulates this response through activation of the ERK-NF-κB pathway." (PMID 21931742, 2011). "In contrast, beneficial effects of TRPV1 antagonism in ameliorating SIRS and MODS in sepsis were diminished when endogenous synthesis of H2S was blocked as seen in septic mice received PAG intervention as compared to the same mice treated with capsazepine." (PMID 21931742, 2011).
Sepsis (continued). "TRPV1 endogenous agonists such as N-oleoyldopamine (OLDA) induce IL-10 by activating TRPV1 in the central nervous system to reduce inflammatory responses and improve endotoxemia and sepsis outcomes." (PMID 40007993, 2025). "Similarly, investigations using the CLP model have unveiled the intricate effects of TRPV1 deletion or activation on local inflammation and SIRS, underscoring the multifaceted nature of TRP involvement in sepsis pathogenesis." (PMID 38731999, 2024). "Given a functional link between SHANK3 and TRPV1 in DRG primary sensory neurons and heat sensation, we evaluated whether peripheral TRPV1 is important for sepsis-induced hypothermia." (PMID 36845137, 2023). "Our data are novel in identifying a role for TRPV1 expressed in the CNS, and endovanilloids, such as OLDA and NADA in modulating peripheral immune responses and determining outcomes of acute inflammation and sepsis." (PMID 35610647, 2022). "There is also evidence of a shift of TRPV1 function from anti-inflammatory to pro-inflammatory in systemic inflammatory response syndrome (SIRS) and sepsis models as an organism ages, shedding light on another factor to consider when utilizing TRPV1-targeted therapy in older patients." (PMID 34200205, 2021). "Recently, a protective role for transient receptor vanilloid 1 (TRPV1), a nonselective cation channel found on both neuronal and nonneuronal cells, was suggested in bacteria-induced sepsis." (PMID 25242870, 2014). "Collectively, our results established H2S stimulation of TRPV1 and the downstream release of SP as a key element in the transition of infection and SIRS to MODS in sepsis, and identified TRPV1 antagonist as a possible therapeutic target for the treatment of polymicrobial sepsis." (PMID 21931742, 2011).
psoriasis (30 papers, 2017 to 2026). An autoimmune condition characterized by red, well-delineated plaques with silvery scales that are usually on the extensor surfaces and scalp. "We first showed that topical application of HCRG21 exhibits therapeutic effects on ACD and psoriasis by inhibiting inflammatory immune responses and relieving clinical manifestations via TRPV1-associated suppression of cytokine gene expression." (PMID 41226679, 2025). "Consistently, the area of Munro micro-abscesses and psoriasis-associated angiogenesis was significantly reduced in TRPV1-deficient mice." (PMID 38474002, 2024). "Growing evidence suggests the involvement of multiple TRP subtypes in the pathogenesis of psoriasis, including altered expression of vanilloid subtypes, such as TRPV1, TRPV3, TRPV4, TRPV6, the canonical TRPC6, and melastatin TRPM8 in patients." (PMID 41689746, 2026). "Although there are still few studies on the role of TRPs in the therapies currently used for psoriasis, there is evidence of the activation of TRPV1 and the TRPA1 subtypes in the adverse effects of topical pharmacotherapy and phototherapy." (PMID 41689746, 2026). "Previous studies have shown that the Transient Receptor Potential Vanilloid 1 (TRPV1) channel is closely related to the development of various chronic inflammatory skin diseases, such as psoriasis, dermatitis, rosacea, herpes zoster, and prurigo nodularis." (PMID 41226679, 2025). "To assess the contribution of TRPV1+ nociceptors in ASIC3-dependent skin inflammation in the mouse psoriasis model, we treated Asic3+/+ and Asic3−/− mice with resiniferatoxin (RTX)." (PMID 38902277, 2024). "The overexpression of TRPV1 in pruritic skin correlates positively with the intensity of psoriasis itching." (PMID 38474002, 2024). "Xanthotoxin, a naturally occurring furanocoumarin with established clinical applications for psoriasis treatment, exerts therapeutic effects by decreasing TRPV1 activity and expression in the DRG and inhibiting immune responses." (PMID 38474002, 2024). "Another drug is CT327/SNA-120, a topical TRPV1 pathway inhibitor that demonstrated its safety and efficacy in a phase IIb clinical trial for psoriasis." (PMID 37511138, 2023). "The endogenous lipid mediator resolvin D3 has been shown to reduce TRPV1-dependent acute itch and chronic psoriasis itch." (PMID 37953876, 2023). "A study reported increased TRPV1 mRNA expression in peripheral blood mononuclear cells (PBMCs) of patients with psoriasis." (PMID 36874007, 2023). "In the imiquimod (IMQ) induced psoriasis model, dermal dendritic cells (dDCs) were imaged in contact with cutaneous sensory neurons expressing TRPV1 and NaV1.8." (PMID 34200205, 2021). "In the skin of AD and psoriasis patients, the expression of these receptors such as phospholipase A2, substance P, Nav1.7, and TRPV1 was positively correlated with the degree of skin lesions." (PMID 33708782, 2021). "Activation of sensory neurons innervating the skin and TRPV1 (transient receptor potential vanilloid 1) are emerging as critical components in the pathogenesis of psoriasis, but little is known about their endogenous inhibitors." (PMID 33204332, 2020). "This research suggests that TRPV1+ nociceptive neurons play a crucial role in the Th17 immune response via the release of neuropeptides from free terminals in psoriasis." (PMID 33133059, 2020). "Further, previous studies showed that RTX-mediated ablation of the TRPV1-positive sensory fibers reduces imiquimod (IMQ)-induced psoriasis-like ear skin inflammation resulting from activation of the IL-23/IL-17 pathway in the dermal dendritic cells/γδ T cells." (PMID 29081531, 2017). "Despite similar results of proinflammatory cytokine inhibition and hematological parameters, HCRG21 revealed a more prominent repairing effect in a psoriasis-like mouse model than in an ACD-like model, which can be associated with greater involvement of TRPV1 in psoriasis development." (PMID 41226679, 2025).